EEF1A2 (eukaryotic translation elongation factor 1 alpha 2)
Diseases named in the same sentence as EEF1A2 in open-access papers (continued):
Sharing a sentence is not in itself a finding about the gene and the disease.
gastric cancer (20 papers, 1994 to 2025). A primary or metastatic malignant neoplasm involving the stomach. "A pivotal role for EEF1A2 emerged in a recent study in gastric cancer revealed that METTL13, which is linked to cancers in humans, works together with EEF1A2 in a loop that causes abnormal levels of the cancer-promoting gene HN1L." (PMID 38172654, 2024). "In general, the EEF1A2 protein displayed a significant upregulation (P < 0.001) in gastric cancer tissues, which was associated with an unfavorable prognosis for patients." (PMID 38172654, 2024). "This study presents a compelling shift in our understanding of the molecular intricacies underlying gastric cancer development, shedding light on the multifaceted roles of EEF1A2 and HSPB8 in this context." (PMID 38172654, 2024). "Moreover, the hazard ratio analysis in the STAD dataset indicated that EEF1A2 has a notably high hazard ratio, indicating a potential association with poor prognosis in gastric cancer." (PMID 38172654, 2024). "The persistence of these epigenetic alterations from early intramucosal gastric cancers (IMCs) to advanced stages, as confirmed by The Cancer Genome Atlas (TCGA) data, positions eEF1A2 as a progression biomarker." (PMID 40806463, 2025). "In gastric cancer, eEF1A2 demonstrates tumor-specific hypomethylation and overexpression linked to the pro-tumorigenic Hedgehog signaling pathway." (PMID 40806463, 2025). "Utilizing a population-based tissue microarray constructed from 129 patients who had undergone either radiotherapy or chemotherapy and 24 randomly chosen normal gastric tissues, a pioneer study was undertaken to study the role of EEF1A2 in gastric cancers." (PMID 38172654, 2024). "A recent study conducted in 2023 has demonstrated elevated levels of EEF1A2 in gastric cancer cell lines." (PMID 38172654, 2024). "EEF1A2 mRNA levels were also found to be upregulated in a subset of the gastric cancer tissues compared with adjacent normal tissues." (PMID 38172654, 2024). "Assessment of relative EEF1A2 proteins in 12 paired gastric cancer and corresponding normal mucosa via western blotting confirmed that EEF1A2 protein levels were significantly higher in tumor tissues." (PMID 38172654, 2024). "In gastric cancer, the observed overexpression of EEF1A2 has been established as an independent indicator for predicting poor prognosis." (PMID 38172654, 2024). "Possible contributions of epigenetic regulation to expression are suggested by studies showing that treatment of gastric cancer cell lines with demethylating agents resulted in increased EEF1A2 expression." (PMID 20505761, 2010). "Notably, EEF1A2 appears to function as an oncogene in the progression of gastric cancer, exerting its influence through the promotion of HSPB8." (PMID 38172654, 2024). "For gastric cancer, apart from EEF1A2 no other translation elongation factor showed significant change in expression in tumors, in Oncomine analysis." (PMID 29342219, 2018).
epilepsy (19 papers, 2013 to 2026). A brain disorder characterized by episodes of abnormally increased neuronal discharge resulting in transient episodes of sensory or motor neurological dysfunction, or psychic dysfunction. "This group found that the introduction of three common autism- and epilepsy-associated variants of EEF1A2 (G70S, E122K, and D252H) results in decreased de novo protein synthesis and reduced translation elongation in HEK cells." (PMID 41509464, 2026). "His latest publication reveals that mutations in EEF1A2 result in translational dysfunction and alterations in actin binding, which are associated with autism spectrum disorders, epilepsy, and intellectual disabilities." (PMID 38410675, 2024). "EEF1A2 gain of function was shown to cause neurodevelopmental disorders, including epilepsy and intellectual disability." (PMID 37474567, 2023). "In humans, mutations in the eEF1A2 gene have been demonstrated to cause intellectual disability, autism, seizures, and epilepsy, and, thus, the actions of eEF1A2 in human neurons ensure normal neurodevelopment." (PMID 35741005, 2022). "A specific homozygous mutation p.(P333)L in the EEF1A2 gene product was reported in children with global developmental delay, epilepsy, and cardiomyopathy." (PMID 33102526, 2020). "One such gene is EEF1A2, encoding a neuromuscular specific translation elongation factor, which has been found to be mutated de novo in five cases of severe epilepsy." (PMID 27441201, 2016). "We have identified a series of further novel de novo missense mutations in EEF1A2 in patients with epilepsy, and thus build on the recently expanding evidence implicating EEF1A2 as a key player in a subset of related neurological syndromes." (PMID 27441201, 2016). "EEF1A2 should be considered as a causative gene not only in cases of epileptic encephalopathy but also in children with less severe epilepsy and intellectual disability." (PMID 27441201, 2016). "The recent discovery of missense mutations in eEF1A2 that cause epilepsy, severe intellectual disability and autism is likely to cause more focus on the role of eEF1B binding, as the G70S mutation abuts the eEF1B binding site." (PMID 25436608, 2014). "Finally, in the group of genes related to epilepsy, we found a variant in the EEF1A2 gene that resulted in a VUS probably converted to LP change in the patient AUT149." (PMID 38003033, 2023). "In addition, eEF1A2 mutation in patients is associated with neurological symptoms and the following clinical features: severe intellectual disability, facial deformity, psychomotor developmental delay, autism and epilepsy." (PMID 26918757, 2016). "However, the recent discoveries 11 of a heterozygous missense mutation in eEF1A2 in two separate individuals with intractable early‐onset epilepsy and severe intellectual disabilities may shed some light on this." (PMID 24460877, 2013). "One recently discovered human single gene disorder is EEF1A2 related epilepsy, for which model systems are badly needed." (PMID 31950975, 2020). "We also show that the presence of biallelic mutations in eEF1A2 in mice can result in seizures and sudden death, providing the first evidence of a link between eEF1A2 and epilepsy in a model organism." (PMID 28378778, 2017). "However, if the epilepsy-causing missense mutations seen in humans in fact represent a toxic gain of function, our new Del2 and Ins4 lines could provide an important resource in which to test the effects of expression of mutant eEF1A2 in the form of human mRNA." (PMID 31950975, 2020).
colorectal cancer (14 papers, 2012 to 2025). A primary or metastatic malignant neoplasm that affects the colon or rectum. "In a recent study, SNX16 was highly expressed in colorectal cancer and activated the c-Myc signaling pathway by upregulating eEF1A2, thereby promoting colorectal cancer development." (PMID 35482720, 2022). "It should be emphasized that MECOM, eEF1A2, and U1 risk alleles have shown detrimental effects in other inflammatory diseases including human IBD and colorectal cancer." (PMID 33432064, 2021). "EEF1A2 was significantly downregulated in the colorectal cancer group, compared to normal." (PMID 29342219, 2018). "In colorectal cancer, lysine acetyltransferase 8 (KAT8) induces lactylation at the K408 site of the eukaryotic translation elongation factor 1 alpha 2 (eEF1A2)." (PMID 40589733, 2025). "Oncomine analysis of colorectal cancer with the pre-specified thresholds didn’t return any datasets with significant difference in mRNA levels, for EEF1A1, EEF1A2, EEF1B2, EEF1G and EEF2." (PMID 29342219, 2018).
lung carcinoma (14 papers, 2009 to 2025). "In humans, eEF1A2 has been shown to have oncogenic properties when inappropriately overexpressed, and has been implicated in ovarian, breast, pancreatic, liver and lung cancer, although the mechanism for overexpression remains elusive, and no mutations have been identified in ovarian tumors." (PMID 19636410, 2009). "EEF1A2 was initially identified as a putative oncogene in lung cancer using a functional genomics approach." (PMID 38172654, 2024). "Subsequent studies identified EEF1A2 as a putative oncogene across various cancers, including breast, liver, gastric, pancreatic, and lung cancers." (PMID 38172654, 2024). "In agreement with the observation obtained in lung cancer cell lines, EEF1A2 was expressed in 32% of the cases." (PMID 38172654, 2024). "Overexpression of many factors predicted poor prognosis in breast (EEF1D, EEF1E1, EEF2) and lung cancer (EEF1A2, EEF1B2, EEF1G, EEF1E1)." (PMID 29342219, 2018). "On the other hand, a sizeable number of datasets (eight in total) spanning across five studies (Bhattacharjee, Steerman, Beer, Su, Selamat) indicated increased transcript levels of EEF1A2 in lung cancer." (PMID 29342219, 2018). "Overexpression of most factors predicted a poor prognosis in breast (EEF1D, EEF1E1, and EEF2) and lung cancer (EEF1A2, EEF1B2, EEF1G, EEF1E1) in KM analysis." (PMID 29342219, 2018). "There is increasing evidence to indicate that EEF1A2 is a candidate oncogene, highly expressed in some human breast, ovarian, and lung cancers." (PMID 20505761, 2010). "This is consistent with expression data as this variant is overexpressed in lung adenocarcinoma cell lines while the EEF1A2 gene is amplified in lung cancer cell lines." (PMID 19636410, 2009). "It was also noteworthy that a recent preclinical study demonstrated that EEF1A2 knockdown suppresses lung cancer brain metastasis by inhibiting the BCL10/NFκB pathway and reversing EMT, further validating the therapeutic potential of targeting eEF1A isoforms in advanced cancers." (PMID 40806463, 2025). "In addition, high-resolution analysis of genomic aberration by metaphase and comparative genomic hybridization array identify the involvement of the 20q region, suggesting the potential role of eEF1A2 as a candidate tumor gene in lung cancer cell lines." (PMID 25905039, 2015). "Therefore, the overexpression of eEF1A2 and KCIP-1 in lung tumor samples strongly suggests that both proteins could be involved in lung adenocarcinoma and could be potential therapeutic targets in lung cancer." (PMID 25905039, 2015).
breast tumors (13 papers, 2005 to 2024). "The presence of increased levels of eEF1A2 in breast tumours may provide a useful new diagnostic marker." (PMID 16156888, 2005). "However, high EEF1A2 protein expression was associated with significantly increased 20-year survival probability in women with serous ovarian tumors, or in primary breast tumors, and this protective effect is thought to be due to EEF1A2’s high expression in reducing the aggressiveness." (PMID 22860045, 2012). "The eEF1A2 is hardly detectable in normal human breast tissue but the expression of eEF1A2 is strongly upregulated in most of breast tumors." (PMID 25905039, 2015). "We have shown that the putative oncogene eEF1A2 is upregulated in a high proportion of breast tumours." (PMID 16156888, 2005). "The genomic region to which eEF1A2 maps, 20q13, had been known for many years to be amplified in a high proportion of ovarian and breast tumours, but the EEF1A2 gene maps closer to the telomere than the region previously implicated." (PMID 16156888, 2005). "Using these isoform-specific antibodies, we show that eEF1A2 expression is barely detectable in normal human breast tissue, but that the gene is moderately to strongly expressed in 63 % of breast tumours examined." (PMID 16156888, 2005). "We report the novel finding that although eEF1A2 is barely detectable in normal breast it is moderately to strongly expressed in two-thirds of breast tumours." (PMID 16156888, 2005). "Overall then, 40 out of 63 breast tumours (63%) examined by immunohistochemistry showed significant overexpression of eEF1A2." (PMID 16156888, 2005). "Overexpression of EEF1A2 has also been seen in breast tumors and it is one of the genes in the 76-gene signature as identified in the ER-positive subset of 115 primary breast tumors that represent a strong prognostic factor for patients at high risk for developing metastases." (PMID 26892682, 2016). "High levels of eEF1A2 proteins are detected in 60% of primary breast tumors and metastases, but not in normal epithelium." (PMID 25905039, 2015). "Notably, representing 22Rv1, DU-145 and PC-3 cell lines different stages of tumour progression, it is not excluded that lower levels of eEF1A2 could be predictable of the outcome as found for breast tumours." (PMID 22095224, 2012).
Intellectual disability (13 papers, 2013 to 2026). "In several reports, variants in EEF1A2 have been associated with autistic features, intellectual disability, and epilepsy." (PMID 41509464, 2026). "Overexpression of eEF1A2 has been reported to be linked with a variety of tumors, and mutations in EEF1A2 are related to a new type of epilepsy syndrome and intellectual disability." (PMID 35127825, 2021). "There was also overlap for genes involved in intellectual disabilities, including AFF2, AIFM1, CA8, EEF1A2, MLC1, and XYLT1, but statistically the overlap is not significant." (PMID 32393163, 2020).
ovarian tumors (13 papers, 2005 to 2024). "In the meantime, eEF1A2 could provide a useful new diagnostic marker for a sub-set of ovarian tumours, and ultimately a possible target for therapy." (PMID 17437010, 2007). "Another report examined EEF1A2 expression at both RNA and protein levels (using isoform-specific antibodies for EEF1A1 and EEF1A2) in histologically defined ovarian tumor subtypes serous, endometrioid, mucinous, and clear cells." (PMID 38172654, 2024). "Using fluorescence in situ hybridization (FISH), the authors found EEF1A2 gene amplification in 25% of primary ovarian tumor samples (14 of 53)." (PMID 38172654, 2024). "The most abundant LAIR-1 binding protein was eEF1A2, a protein that is overexpressed in 30% of ovarian tumors." (PMID 32628130, 2020). "The oncogenic properties of eEF1A2 have also been studied in different ovarian tumors and established cell lines." (PMID 25905039, 2015). "High levels of eEF1A2 expression was observed in 30% all the primary ovarian tumors, 50% of serous tumors, 30% of endometrioid tumors, 19% of mucinous tumors, and 8% of clear-cell tumors." (PMID 25905039, 2015). "We have carried out a number of analyses of ovarian tumour DNA to establish the mechanistic basis of the overexpression of eEF1A2." (PMID 17437010, 2007). "We have now set out to examine eEF1A2 expression in a panel of ovarian tumours of defined histological subtypes." (PMID 17437010, 2007). "Approximately 50% of ovarian tumors and cell lines have copy number increases in 20q, genes amplified therein, including EEF1A2, may play a central role in the pathogenesis of sporadic and hereditary ovarian carcinoma." (PMID 23347343, 2013). "Previous studies of ovarian tumors that aberrantly express EEF1A2 at high levels also ruled out contributions of mutation or changes in the methylation status of the gene, and showed that levels of expression did not correlate with gene amplification." (PMID 20505761, 2010). "We show in a panel of ovarian tumours that while a high proportion of clear cell carcinomas overexpress eEF1A2, a far smaller proportion of serous, endometrioid and mucinous tumours have high levels of eEF1A2 expression." (PMID 17437010, 2007). "We therefore, went on to establish whether the methylation status of the EEF1A2 gene differs between ovarian tumours and normal ovarian tissue." (PMID 17437010, 2007). "Using northern blotting, EEF1A2 mRNA was detectable in 3 of the 11 primary ovarian tumor samples analyzed, but it was absent altogether in normal ovarian tissues." (PMID 38172654, 2024). "We can not detect eEF1A2 expression in the vast majority of ovarian tumours examined, however, which argues against the idea that tumour overexpression is simply a feature of the cells from which the tumours have arisen." (PMID 17437010, 2007).